MIR6516 (microRNA 6516)
Synonyms: hsa-mir-6516
Gene: MicroRNA gene on chromosome 17 (77,089,417 to 77,089,497, forward strand). Ensembl gene ENSG00000284250.
Gene Ontology:
Biological process: RNA processing
Cellular component: nucleolus
Homologues: Orthologues: chimpanzee MIR6516 (100% identical).